CXCL10 (C-X-C motif chemokine ligand 10)
Diseases named in the same sentence as CXCL10 in open-access papers (continued):
Sharing a sentence is not in itself a finding about the gene and the disease.
inflammatory skin disease (8 papers, 2012 to 2024). Inflammatory skin disorders covers a broad category that includes many conditions ranging in severity, from mild itching to grave medical health complications These disorders are common in people of all ages and races. "Other genes, such as IL-21R, GSDMC, CCR7, TLR9, HAS1/3, IL-17A, IL-22, and CXCL10, have been previously identified as genes associated with various inflammatory skin disorders." (PMID 38612783, 2024). "When the epidermal barrier of the skin is damaged by physical or chemical stimuli, many cytokines (IL-1β, IL-6, TNF-α, IL-5, and TSLP) and chemokines (MCP-1, RNATES, TARC, MDC, CXCL8, and CXCL10) are expressed in stimulated keratinocytes to promote the progression of inflammatory skin diseases." (PMID 36670888, 2022). "It has been shown to promote a pro-inflammatory response by priming keratinocytes, macrophages or inflammatory dendritic epidermal cells (IDEC) for TNFα, CXCL10 and IL-23 production respectively, and therefore may contribute to the elicitation of inflammatory skin diseases." (PMID 22761702, 2012). "Another previous study reported findings similar to our data, showing differences in the expression of CXCL9, CXCL10, and CXCL11 in different types of inflammatory skin disease, including lichen planus, chronic discoid lupus, and psoriasis." (PMID 28436448, 2017). "Specifically, chemokines CXCL9, CXCL10, and CXCL11 were involved in the T cell recruitment and infiltration in inflammatory skin diseases." (PMID 28427244, 2017).
juvenile dermatomyositis (8 papers, 2013 to 2024). Juvenile dermatomyositis (JDM) is the early-onset form of dermatomyositis (DM), a systemic, autoimmune inflammatory muscle disorder, characterized by proximal muscle weakness, evocative skin lesion, and systemic manifestations. "Muscular cells, although being not the main source in vivo, can produce CXCL10 during inflammatory conditions, as shown by immunohistochemical studies in skeletal muscle fibers of patients with juvenile dermatomyositis." (PMID 24204948, 2013).
osteoarthritis (8 papers, 2013 to 2024). A noninflammatory degenerative joint disease occurring chiefly in older persons, characterized by degeneration of the articular cartilage, hypertrophy of bone at the margins and changes in the synovial membrane. "The osteoarthritis control patients (prior to arthroplasty) also showed a less pronounced IL-8 and CXCL-10 elevation as compared with the healthy controls." (PMID 30372661, 2018). "Higher levels of CXCL10 and other chemokines have indeed been detected both in synovial fluid and synovial tissue of RA patients compared to osteoarthritis patients." (PMID 28148302, 2017). "The expression levels of TCA1, TLR7, MMP9, CXCL10, CXCL13, HLA-DRA, and ADIPOQSPP1 were significantly higher in the IL-1β-induced group than in the osteoarthritis group in an in vitro qPCR experiment." (PMID 35734177, 2022).
peritonitis (8 papers, 2013 to 2025). Inflammation of the peritoneum (tissue that lines the abdominal wall and covers most of the organs in the abdomen). "In a peritonitis model induced by CLP, B cells produce CXCL10 in response to type I interferon secreted during peritonitis and amplifies the inflammatory responses, leading to efficient bacterial eradication." (PMID 27146354, 2016). "TMs decreased the association of HuR with genes involved in chemotaxis and immune response, including Cxcl10, Il1b and Cd40, reducing their expression and protein secretion in primary murine bone marrow-derived macrophages and in an LPS-induced peritonitis model." (PMID 36912171, 2023). "The Cxcl13+ FALC cover cell cluster was distinguished by the expression of the monocyte chemoattractants Ccl2 and Ccl7 and the neutrophil chemoattractants Cxcl1 and Cxcl10, suggesting a role for these cells in orchestrating the recruitment of inflammatory cells during peritonitis." (PMID 32294409, 2020). "In murine peritonitis models, blockage of CXCR3 or CXCL10 in conjunction with antibiotic therapy reduced migration of NK cells to the peritoneal cavity and improved survival, even if applied after induction of peritonitis." (PMID 31440239, 2019).
rectal cancer (8 papers, 2015 to 2025). A primary or metastatic malignant neoplasm that affects the rectum. "In the present de novo meta-analysis study, we found three genes: CXCL10, IDO1 and AKR1C3 associated to chemo-resistance in rectal cancer patients." (PMID 26359356, 2015). "CXCL10, IL12A, CD247 and ITGB1 were identified as predictive markers for the response to neoadjuvant treatment in rectal cancer in previous studies." (PMID 38406803, 2024). "When investigating the expression of these chemokines by rectal cancer-infiltrating pDCs, we observed that CCL4- or CXCL10-expressing pDCs are present in the majority of post-nRCT tumor specimens, whereas they are absent in pre-nRCT tissue samples." (PMID 30984181, 2019). "Gene expression levels of GZMA, GZMB, PRF1, IFNG and chemokine CXCL10 were compared between responsive versus non-responsive rectal cancer patients." (PMID 35534879, 2022). "Hence, mouse CT26 rectal cancer cells, which produce negligible amounts of CXCR3 ligands, were engineered to express murine CXCL10." (PMID 29163806, 2017).
renal cell carcinoma (8 papers, 2012 to 2025). "In renal cell carcinoma, endogenous CXCL9 was closely implicated in the antitumor effects that were produced by IL‐2 64 and IL‐12 (also producing CXCL10) 65 by inhibiting tumor angiogenesis and infiltration of CD8+ T lymphocytes, respectively." (PMID 27726306, 2016). "Sporadic instances of renal cell carcinomas in humans exhibit heightened expression levels of CXCL9, CXCL10, and CXCL11, hence facilitating the recruitment of T cells that possess CXCR3 and CCR5 receptors." (PMID 38730579, 2024). "In renal cell carcinoma (RCC), it was reported that high‐dose IL‐2 treatment in 20 patients elevated the plasma levels of CXCR3 ligands (CXCL9, CXCL10, and CXCL11), sequentially, forming an angiostatic environment." (PMID 27726306, 2016). "Renal cell carcinoma, a typical immune-excluded tumor, is considered to lack the expression of some chemokines related to T cell recruitment, such as CXCL9, CXCL10, CXCL11, CXCL13, CX3CL1, CCL2, and CCL5, in its TME, but the specific mechanisms underlying this lack of chemokines remain unclear." (PMID 36397015, 2022).
respiratory failure (8 papers, 2020 to 2025). The significant impairment of gas exchange within the lungs resulting in hypoxia, hypercarbia, or both, to the extent that organ tissue perfusion is severely compromised. "Multivariate regression analysis showed that serum IFN-α levels higher than the cut-off value of 107 pg/mL showed the highest OR for hypoxemic respiratory failure, demonstrating a greater than two-fold stronger association as compared with IL-6 and CXCL10." (PMID 37731495, 2023). "Besides expression of pro-inflammatory cytokines, such as IL-1β and TNF-α, the expression of chemokines CCL2, CCL3, CCL20, CXCL1, CXCL3, CXCL10, IL-8 was shown likely to contribute to clinical observation of excessive inflammatory tissue damage, lung injury, and respiratory failure." (PMID 33362782, 2020).
B-cell lymphoma (7 papers, 2014 to 2024). "In Addition, IL‐12 and Th1‐derived IFN‐γ exerted antitumor effects through the inhibitory effects of endogenous CXCL9 and CXCL10 on tumor vasculature in human Burkitt's lymphoma 51 and in B‐cell lymphoma 52, respectively." (PMID 27726306, 2016). "Despite the strong impact on T cell recruitment, we observed a mild effect of CXCL10 and IFNγ blockade in impairing the efficacy of CD20-TCB in a model of B cell lymphoma in humanized mice." (PMID 33406104, 2021). "The role of CXCL10 in B cell lymphomas has not been studied well, but it is known that its receptor CXCR3 is expressed on a small subset of B cells." (PMID 30301877, 2018).
chronic hepatitis (7 papers, 2007 to 2024). An active inflammatory process affecting the liver for more than six months. "Despite clear induction of Cxcl10 in KC and reduction in IM, other ISGs showed an irregular regulation, indicating an ambiguous antiviral response by KC and IM during chronic hepatitis." (PMID 27812182, 2016). "In addition, CXCL10 has been found in hepatocytes surrounded by infiltrative mononuclear cells in chronic hepatitis." (PMID 32641985, 2020). "The slopes of CXCL9, CXCL10, CXCL11, and TIGIT were higher in T cells of chronic hepatitis patients than in those of patients with HBeAg+ chronic infection and HBeAg− chronic infection, indicating that the expression of these genes was increased in the corresponding cell types." (PMID 39135698, 2024).
cutaneous leishmaniasis (7 papers, 2012 to 2023). Leishmaniasis affecting the skin. "Recent findings point to CXCL-10 (C-X-C motif chemokine 10) as a potential tool for immunotherapy of cutaneous leishmaniasis, since this molecule favors a shift towards a Th1 pro-inflammatory response." (PMID 36703216, 2023). "Ritter and Korber demonstrated the key role of MIG in the self-healing of localized cutaneous leishmaniasis, confirming that lesions exhibited a strong expression of Th1-associated chemokines, such as CCL2/MCP-1, CXCL9/MIG, and CXCL10/IP-10." (PMID 37242376, 2023). "and cutaneous leishmaniasis involves the production of multiple Th1-associated chemokines including CCL2, CCL7, CXCL9, and CXCL10." (PMID 34543348, 2021). "CXCL10 and CXCL9 were also identified as the most highly “induced” genes in comparing lesion transcript profiles with normal skin of patients with American cutaneous leishmaniasis, consistent with their roles in inflammatory cell recruitment." (PMID 31419223, 2019).
endotoxemia (7 papers, 2010 to 2024). "Cytokine storm and endotoxemia may cause a decrease in LV EF, but some chemokines (CXCL9 and CXCL10) suggest a direct negative inotropic effect." (PMID 36124439, 2023).
epilepsy (7 papers, 2014 to 2025). A brain disorder characterized by episodes of abnormally increased neuronal discharge resulting in transient episodes of sensory or motor neurological dysfunction, or psychic dysfunction. "Cytokine assays showed that cenobamate behaved similarly to cannabidiol by reducing the levels of Ccl5 and Cxcl10, both of which have been known to be mediators of inflammation in epilepsy." (PMID 40848130, 2025). "Studies have shown that A1 astrocyte promoted neuronal ferroptosis via C‐X‐C motif ligand 10/chemokine (C‐X‐C motif) receptors 3 (CXCL10/CXCR3) axis in epilepsy." (PMID 39801259, 2025). "Recently, a therapy based on the use of anti-CXCL10 monoclonal antibodies has shown some promises in the treatment of animal models of epilepsy." (PMID 32521797, 2020). "The expression of CXCL10 has been reported in several forms of epilepsy and the levels of CXCL10 in blood or cerebrospinal fluid (CSF) could be used as biomarkers of the progression of the disease." (PMID 32521797, 2020).
Hashimoto thyroiditis (7 papers, 2021 to 2025). An autoimmune disorder caused by the production of autoantibodies against thyroid tissue. "When combined with myo-inositol, selenium also lowers TSH levels and reduces CXCL10, a chemokine linked to lymphocytic infiltration and tissue damage in Hashimoto’s thyroiditis." (PMID 41157208, 2025). "Moreover, CSF1 induces pro-tumoral M2 macrophage polarization through binding to CSF1R, whereas CXCL9 and CXCL10 are involved in T-cell recruitment manifested as chronic lymphocytic thyroiditis, which has been associated with a better prognosis of PTC." (PMID 35515000, 2022). "Hashimoto's thyroiditis is a disease also mediated by Th1 cells, in which IFN-γ and its associated chemokines, such as CXCL10, play an important role." (PMID 34630818, 2021). "Myeloid cells express chemokines (CXCL12 and CXCL10) as chemoattractants to recruit T cells expressing their receptors (CXCR4 and CXCR3), which is consistent with the pathological findings indicating chronic lymphocytic thyroiditis in P1 and P2 patients." (PMID 35515000, 2022). "Recent studies indicate that chemokines CXCL9, CXCL10 and CXCL11, induced by INF-γ, may play an important role in the early development of Hashimoto’s thyroiditis." (PMID 36139446, 2022). "Myeloid cells expressed genes (CXCL10 and CXCL12) for chemokines as chemoattractants to recruit T cells expressing CXCR4 and/or CXCR3 in T1 and T2 samples, but not in T3, which was in accordance with the histological assessment that indicated chronic lymphocytic thyroiditis in T1 and T2 samples." (PMID 35515000, 2022).
localized scleroderma (7 papers, 2013 to 2025). Localized scleroderma is the skin localized form of scleroderma characterized by fibrosis of the skin causing cutaneous plaques or strips. "Moreover, elevated levels of CXCL9 and CXCL10 were detected in the serum of patients with morphea, consistent with increased transcription and expression of CXCL9 in skin lesions, and this increase has been linked to inflammation and disease activity." (PMID 39685593, 2024). "Notably, while our studies confirm the value of CXCL10 in the VEDOSS population, this is not a specific marker for SSc as increased levels of CXCL10 have been shown in SLE, DM as well as localized scleroderma." (PMID 39700423, 2025).
lymph node metastasis (7 papers, 2020 to 2025). "Third, CXCL10 is an independent predictor of lymph node metastasis of the primary tumor, and co-expression of CXCL10/CXCR3 was associated with postoperative recurrence." (PMID 33195424, 2020). "Survival analysis was performed to assess the value of CXCL10 as an independent predictor of the existence of lymph node metastases with its corresponding receptor CXCR3." (PMID 33195424, 2020). "Multivariate logistic regression analysis identified CXCL10 expression as an independent predictor of lymph node metastasis." (PMID 33195424, 2020). "Moreover, the results of Model 2 further identified CXCL10 as an independent predictor of the existence of lymph node metastases." (PMID 33195424, 2020). "We also found that the expression of the three LINC01871‐related mRNAs, namely, IDO1, CXCL10, and GBP4, was highly negatively correlated with TNM stage, lymph node metastasis, and liver metastasis." (PMID 38083905, 2023). "Then we analyzed the levels of both Nrf2 and CXCL10 measured in follicular fluids of the study participants divided in three groups: healthy controls, BC patients without lymph node metastasis and with lymph node metastasis." (PMID 36984881, 2023). "However, in the present study, CXCL10 expression was not significantly higher in lymph node metastases than bone metastases (p = 0.1850)." (PMID 33195424, 2020).
Myalgia (7 papers, 2014 to 2024). "IL-6, CXCL-10/IP-10, CRP and presence of knee pain and myalgia were found to significantly predict persistence of post CHIKV musculoskeletal pain." (PMID 25343623, 2014).
nasopharyngeal carcinoma (7 papers, 2017 to 2026). A carcinoma arising from the nasopharyngeal epithelium. "Based on these references CXCL9, CXCL10 and CXCL11 are likely to influence tumorigenesis from inflammation-related nasopharyngeal cancer." (PMID 32986378, 2020). "In nasopharyngeal carcinoma (NPC), LMP1 induces CXCL10 expression, upregulates IL-8, macrophage inflammatory protein (MIP)-1 α and MIP-1 β to promote lymphocyte infiltration." (PMID 32595759, 2020). "ZIC2 and OVOL1 may function in nasopharyngeal carcinoma through targeting significantly up-regulated genes (such as PTGS2, FN1, CXCL9 and CXCL10) in the Transcription factor-differentially expressed gene regulatory network (e.g., ZIC2→PTGS2 and OVOL1→CXCL10)." (PMID 27765529, 2017). "PTGS2, FN1, CXCL9, CXCL10, ZIC2 and OVOL1 might play roles in nasopharyngeal carcinoma." (PMID 27765529, 2017).
nephritis (7 papers, 2020 to 2025). Inflammation of renal tissue. "Consistently, our in vivo data showed that the expression levels of CCL2, CCL3, CCL4, CCL5, CCL19, and CXCL10 increased in the kidney of MRL.Faslpr mice during the development of nephritis." (PMID 37567910, 2023). "Future studies are aimed at investigating the impact of CPT on nephritis by inhibiting Fli-1 modulation of the CXCL10/CXCR3 axis." (PMID 37790939, 2023). "We further expand this knowledge by reporting on the enhanced migratory capability of peripheral blood mononuclear cells towards CXCL10 ex vivo and provide evidence for increased numbers of infiltrating immune cells in kidneys of mice with anti-GBM nephritis." (PMID 32977372, 2020).
neuroblastoma (7 papers, 2015 to 2025). Neuroblastoma (NB) is the most common solid, extracranial childhood tumor. "BIX01294 and UNC0638, both G9a/GLP inhibitors, suppressed astrocytoma and neuroblastoma cell growth while increasing IFN-y-induced expression of CXCL10 mRNA in MYCN-amplified neuroblastoma." (PMID 39766049, 2024). "Using neuroblastoma as a model, CancerPAM analysis of tumour sequencing data identifies optimal knock-in sites for pro-inflammatory cytokines (CXCL10, CXCL11, IFNG), and CancerPAM rankings correlate strongly with target-site specificity and knock-in efficiency, validating its predictive performance." (PMID 41366257, 2025). "In neuroblastoma (NB), MYCN-induced upregulation of the H3K9 methyltransferases G9a and GLP as well as EZH2 can also inhibit IFN-γ-induced expression of CXCL9 and CXCL10." (PMID 39080807, 2024). "In neuroblastoma, G9a and GLP were found to have a positive correlation with MYCN expression, and increased H3K9me2 and H3K27me3 at the CXCL9, CXCL10, and CXCL11 chemokine cluster indicated the potential role of G9a, GLP, and EZH2 in maintaining a ‘cold’ tumor microenvironment." (PMID 39766049, 2024).
pancreatic adenocarcinoma (7 papers, 2014 to 2025). "Previous studies reported that CXCL10 had a negative correlation with the survival time of the patients, suggesting it could be a poor prognostic indicator of pancreatic adenocarcinoma." (PMID 40839565, 2025).
pancreatic ductal adenocarcinoma (7 papers, 2014 to 2024). An infiltrating adenocarcinoma that arises from the epithelial cells of the pancreas. "In pancreatic ductal adenocarcinoma, CXCL10 has been shown to recruit CD4+, CD8+, and CXCR3+ T cells as well as FOXP3+ Tregs27." (PMID 34504204, 2021). "Some chemokines, such as CCL5 (RANTES), CXCL10 and CCL2 induced by TNFα, also have been reported to locally recruit both CAR T cells and endogenous T cells when combined with adenoviral OV and mesothelin-redirected CAR T cells in pancreatic ductal adenocarcinoma model." (PMID 36353540, 2022).
prostate tumor (7 papers, 2016 to 2025). "Together, these results indicate that CXCL10 recruits NK cells, thus contributing to the MSCs-Sirt1-induced prostate tumor suppression in mice." (PMID 27764779, 2016). "Further, in an ex vivo prostate tumor model, celecoxib suppressed intra-tumoral production of the Treg/MDSC-attractant CXCL12 and Treg-attractant CCL22, while increasing the production of the cytotoxic T lymphocyte (CTL) attractant CXCL10." (PMID 32824865, 2020). "However, we found that ARID1A loss did not reduce Cxcl9 and Cxcl10 expression in PCa cells treated with IFN-γ or TNF-α and mouse prostate tumors." (PMID 36435834, 2022).